TSPO (translocator protein)
Diseases named in the same sentence as TSPO in open-access papers (continued):
Sharing a sentence is not in itself a finding about the gene and the disease.
TSPO also shares sentences with these, for which no sentence is quoted: experimental autoimmune encephalomyelitis (6 papers); relapsing-remitting multiple sclerosis (4); acute myocardial infarction (3); autism spectrum disorder (3); cardiovascular diseases (3); Cirrhosis (3); insomnia (3); secondary progressive MS (3); cardiomyopathy (2); colorectal (2); Hypertension (2); liver cancer (2); migraine (2); neuropathic pain (2); obsessive-compulsive disorder (2); oesophageal cancer (2); oral squamous cell carcinoma (2); panic disorder (2); pulmonary TB (2); Seizure (2); spinal cord injury (2); systemic lupus erythematosus (2); acute liver failure (1); adenocarcinoma (1); Adrenal insufficiency (1); adrenocortical neoplasms (1); Allergy (1); autoimmune disease (1); autoimmune encephalitis (1); Autoimmunity (1).
A further 60 diseases each share a sentence with TSPO in 1 paper.